EPCAM (epithelial cell adhesion molecule)
Diseases named in the same sentence as EPCAM in open-access papers (continued):
Sharing a sentence is not in itself a finding about the gene and the disease.
cancer (continued). "Common markers include EpCAM, used for epithelial cancers; CD44 and CD24, which are associated with cancer stem cells; and cytokeratins, such as CK8 and CK18." (PMID 40260304, 2025). "We found that EPCAM is significantly upregulated in CNV cancer cells, while SFN expression is downregulated." (PMID 40244296, 2025). "In this respect, in the absence of TPR-specific CD8pos T cells, the treatment of OvCAR3 and PC3M cancer cells with EpCAM-ReTARGTPRIFNαR149A inhibits proliferation and stimulates cancer cell-secreted CXCL10 (IP-10)." (PMID 40243928, 2025). "Previously, we compared EpCAM-ReTARGTPR and solitomab in terms of cancer cell elimination and T-cell-secreted cytokines." (PMID 40243928, 2025). "Accordingly, more comprehensive targeting strategies are needed, those integrating EpCAM-based approaches with alternative technologies to enhance the efficacy of cancer diagnosis and therapy." (PMID 39996844, 2025). "Decoration of of EpCAMpos cancer cells with EpCAM-ReTARGTPR enables physiological engagement of cognate anti-CMV CD8pos T cells and subsequent effective target cell elimination in the absence of excessive cytokine release." (PMID 40243928, 2025). "EpCAM (Epithelial cell adhesion molecule) is a key cancer stem cell marker involved in cancer progression, making it an important target for both diagnosis and therapy." (PMID 40017594, 2025). "This study explored the pH‐responsive characteristics of the produced lipid NPs and evaluated their effectiveness in cancer cell lines derived from various sources exhibiting elevated levels of EpCAM." (PMID 40391083, 2025). "Downregulation of EpCAM, a transmembrane glycoprotein, favors a poor prognosis and cancer cell invasion of EC." (PMID 40804837, 2025). "Several studies have reported that EpCAM plays critical roles in cancer stemness, cell proliferation, metabolism, angiogenesis, epithelial-to-mesenchymal transition (EMT), metastasis, chemoresistance, and immunomodulation." (PMID 39996844, 2025). "EpCAM was one of the first cancer antigens targeted by antibody-based therapies, and several monoclonal antibodies (mAb) have been used in clinical trials." (PMID 40792441, 2025). "The dominant antigens on cancer cells were EpCAM, MUC-1, TTF-1, Ki67, cytokeratin, and CD56, whose average expression was around 70–60%." (PMID 39941799, 2025). "Epithelial Cell Adhesion Molecule (EpCAM) is a type I transmembrane glycoprotein, approximately 40 kDa in size, expressed in epithelial and epithelial-derived cancers including lung, gastric, colorectal, and other forms of epithelial tumors." (PMID 41357552, 2025). "The selected sdAbs were purified and their anti-cancer activity was validated through specific binding with the EpCAM peptide." (PMID 40017594, 2025). "Fortunately, several anti-EpCAM antibody clones have already been investigated in clinical trials for cancer therapies." (PMID 40792441, 2025). "After 24 h of co-culture, similar >70% cancer cell elimination was detected for EpCAM-ReTARGTPRIFNαR149A and EpCAM-ReTARGTPR." (PMID 40243928, 2025). "EpCAM exhibits widespread and elevated expression across a spectrum of cancers, with a particular emphasis on colorectal malignancies, as evidenced by data from the Gene Expression Profiling and Interactive Analyses (GEPIA) database." (PMID 40057807, 2025). "EPCAM has previously been reported to function as a stem cell marker or a marker for cancer-initiating cells in HCC." (PMID 41228323, 2025). "This assay uses antibody-conjugated ferroparticles that bind with high affinity to CTCs expressing epithelial cell adhesion molecule (EpCAM), a cell-surface protein present in most carcinomas, allowing their isolation with magnets." (PMID 40385463, 2025). "Ber-EP4 is an antibody that targets the epithelial cell adhesion molecule (EpCAM), which is found in most epithelial cells and carcinomas." (PMID 40922881, 2025).
cancer (continued). "EpCAM is regarded as a carcinoma cell-surface marker involved in cell adhesion, proliferation, migration, stemness, and epithelial-to-mesenchymal transition." (PMID 40778224, 2025). "Catumaxomab is a rat/murine-hybrid trifunctional monoclonal BiTE targeting EpCAM x CD3, which was approved back in April 2009 as the first BsAb in the European Union for the treatment for patients with malignant ascites and EpCAM-positive carcinomas." (PMID 40565299, 2025). "EpCAM plays a critical role in tumorigenesis and metastasis of carcinomas and can be a potential prognostic marker for immunotherapeutic strategies." (PMID 40445498, 2025). "Designed ankyrin repeat protein (DARPin) Ec1, a small scaffold protein (18 kDa), binds with high affinity the epithelial cell adhesion molecule (EpCAM) that is overexpressed in several carcinomas." (PMID 40508045, 2025). "Bi-specific antibodies targeting both EpCAM and CD73 can selectively target EpCAM+ carcinoma-derived EVs secreted from various cancer cells and inhibit CD73 EV-mediated immune suppression compared to CD73-targeting alone." (PMID 39996844, 2025). "CTCs of carcinoma origin are believed to express EpCAM and cytokeratins (CKs), common epithelial markers that are frequently used to identify them." (PMID 40429857, 2025). "In an attempt to clarify their role in a cancer-relevant context, we chose breast epithelial MCF7 cells as a well-established model of EpCAM-positive carcinoma cells." (PMID 39572744, 2025). "EpCAM-based capture methods are inherently biased towards capturing CTCs with epithelial cell characteristics and are less effective in carcinomas with downregulated EpCAM expression, such as during epithelial-mesenchymal transition (EMT)." (PMID 40343949, 2025). "EpCAM is an epithelial cell adhesion molecule which plays a role in cell proliferation, migration, and signaling and is frequently overexpressed on the cell surface of several human carcinomas." (PMID 40258059, 2025). "The high-level expression of EpCAM in various carcinomas (e.g. prostate, ovarian, lung, colon, and breast cancers) and metastases, along with its correlation to clinical outcomes, has established it as both a prognostic marker and a therapeutic target." (PMID 40445498, 2025). "EPCAM is highly expressed in numerous malignant tumours, and much research has been conducted on its use as a prognostic marker." (PMID 38291183, 2024). "As EpCAM is primarily expressed on the surface of cancer cells, there has been great interest in the development of EpCAM mAbs." (PMID 38612911, 2024). "To this aim, we first employed a set of antibodies directed against surface (cancer) stem cell markers and adhesion molecules in combination with EpCAM and CD44." (PMID 39246444, 2024). "Epithelial cell adhesion molecule (EpCAM), an epithelial marker for various types of cancer, serves as the primary marker to detect CTCs." (PMID 38746681, 2024). "Other projects that have aimed to detect CTC include “Cancel the cancer,” which targeted the epithelial cell adhesion molecule (EpCAM) biomarker (iGEM Fatih-Medical, 2012), and “cell in CELL” by DUT China A in 2019." (PMID 39351063, 2024). "Further verification by qRT-PCR in clinical samples showed the mRNA expression of EpCAM in cancer tissues was reduced than that in normal tissues in paired and unpaired samples." (PMID 38187284, 2024). "One category is antibody-based immunecapture through cancer cell surface markers, such as epithelial cell adhesion molecule (EpCAM)." (PMID 38675332, 2024). "For optimal recovery of cancer cells, three epithelial-specific markers (EpCAM, EGFR, and cytokeratin) and one EMT marker (Vimentin) were added." (PMID 38469233, 2024). "As evidenced, immunomodulatory agents have been of great interest in the targeting of EpCAM to treat cancer." (PMID 38612911, 2024).
cancer (continued). "EpCAM undergoes crosstalk with several bio-signaling networks that are important for cancer stem cell maintenance and cancer survival." (PMID 38543147, 2024). "Our standardized analysis of 14,832 tumors provides a comprehensive overview on EpCAM immunostaining in malignant tumors." (PMID 38786342, 2024). "Investigation of significantly differently regulated parameters showed that samples from mCRC patients induced less effective ADCC as measured by a reduced LDH release or induction of dead (DAPI+AnnexinV+) EpCAM+ cancer cells." (PMID 39791733, 2024). "For example, the cancer biomarker EpCAM (epithelial cell adhesion molecule) is generally detected using ELISA, PCR and cytometry, but researchers developed an electrochemical biosensor using rGO@TiO2 nanocomposites." (PMID 39091905, 2024). "Chimeric antigen receptor redirected T cells (CAR-T) are another promising avenue of targeting EpCAM in cancer." (PMID 38612911, 2024). "Firstly, we separated CTCs in clinical samples by size effect of microfluidic chips and found that EpCAM/EGFR/Her2 were widely presented as biomarkers in CTCs from peripheral blood of various cancer patients." (PMID 38720360, 2024). "In vitro, VB6-845 displayed high cytotoxicity against EpCAM+ cancer cell lines NIH:OVCAR-3, Caov-3, MCF-7, NCI-H69, HT29, and CAL 27 with nanomolar IC50 values (0.4–1.8 nM)." (PMID 38612911, 2024). "The expression of an EpCAM varies in different cancers with breast and prostate cancer being the highest and neurogenic cancers being the lowest." (PMID 39201281, 2024). "In contrast, mesenchymal EpCAMneg (from MD/PD-SCCs) and full mesenchymal (from PD/S-SCCs) cancer cells lost EpCAM expression." (PMID 39075581, 2024). "While EpCAM exhibited pronounced overexpression across a wide spectrum of cancer types, a notable reduction was observed in KIRC tissues." (PMID 38187284, 2024). "The engraftment of GFP+EpCAM+ cancer cells from WD-SCCs into immunocompetent syngeneic mice gave rise to tumors with a reduced percentage of GFP+EpCAM− cancer cells." (PMID 38914547, 2024). "Data obtained from the public database was harnessed for the comprehensive assessment of the EpCAM expression levels and prognostic and clinicopathological correlations in thirty-three types of cancer." (PMID 38187284, 2024). "EpCAM is also an attractive antigen for targeted therapies, and treatment of malignant ascites in cancer patients with EpCAM-positive tumors with the anti-EpCAM antibody catumaxomab has been approved already in 2009." (PMID 38928484, 2024). "The primary objective of this investigation is to study EpCAM expression in pan-cancer and elucidate its significance in the context of kidney renal clear cell carcinoma (KIRC)." (PMID 38187284, 2024). "CAF-derived Wnt proteins can also induce the expression of CSC markers, such as CD44 and Epithelial cell adhesion molecule (EpCAM), in cancer cells." (PMID 39519109, 2024). "Using our mouse model of cSCC progression, we compared the phosphoproteome profile of full epithelial, EpCAM+ plastic, and mesenchymal EpCAMneg cancer cells by high throughput mass spectrometry analysis." (PMID 39075581, 2024). "Consistent with previous reports, EpCAM exhibited significant overexpression in the majority of cancer types." (PMID 38187284, 2024). "3D-iNET ORION cancer cell line showed high potential to form tumorspheres when embedded in Matrigel matrix and expresses synaptophysin and EpCAM." (PMID 39103560, 2024). "EPCAM, a cell adhesion molecule, is mainly considered a cancer cell surface marker and therapeutic target." (PMID 39286258, 2024). "Epithelial cell adhesion molecule (EpCAM), a pan-epithelial differentiation antigen, is expressed across various cancers and possesses endogenous oncogenic potential." (PMID 38245520, 2024). "The prognostic implications of EpCAM-positive expression in CTCs lack clarity across other cancer types." (PMID 39456890, 2024).
cancer (continued). "Our results evidenced that the expression of cancer stem cell surface markers, including EPCAM, CSF3R, CD34, CD96 and ENG, were significantly different." (PMID 38977778, 2024). "Given its high expression level and immunogenicity, EpCAM is considered as a surface biomarker and potential therapeutic target in human cancers." (PMID 38791091, 2024). "For example, EpCAM (Epithelial cell adhesion molecule) is an epithelial marker widely used in cancer diagnosis but is limited in EpCAM-negative or low-expression tumors." (PMID 39539964, 2024). "This versatility enables the recovery of various cancer cell types with different EpCAM expressions." (PMID 38831912, 2024). "To evaluate the prognostic significance of EpCAM in various cancer types, we conducted univariate Cox regression analysis." (PMID 38187284, 2024). "Epithelial cell adhesion molecule (EpCAM) is currently being considered as a molecular target for immunotherapy of advanced cancer." (PMID 39199590, 2024). "As most of the cancers are of an epithelial origin, a “universal” epithelial marker of cancer, an epithelial cell adhesion molecule (EpCAM) can be used as a common marker for CTCs." (PMID 39201281, 2024). "Gene score matrices were generated using ArchR and used for subsetting cancer datasets for epithelial cells based on epithelial cellular adhesion molecule (EPCAM) scores." (PMID 39623476, 2024). "Beyond its proposed role as a CAM, EpCAM has also been implicated as a CSC marker and mediator of cell proliferation, migration, and gene expression in cancer." (PMID 38612911, 2024). "EpCAM+ITGAV+ cancer cells gave rise to MD/PD-SCCs containing a higher percentage of mesenchymal EpCAMneg and ITGAV+ cancer cells than EpCAM+ITGAV−-derived tumors." (PMID 39075581, 2024). "Herein, a MagLev-based biosensor platformfor exosome detectionwas proposed, and the platform was tested with solubilized ExoMPs,EpCAM as a cancer biomarker, CD151 as an NSCLC biomarker, and CD81as an exosomal biomarker." (PMID 38520356, 2024). "Abnormal expression of EpCAM is a common feature in many cancers, particularly gastrointestinal tumors, suggesting its significance in tumorigenesis and cancer development." (PMID 39184916, 2024). "Epithelial GFP+EpCAM+Vim− cancer cells made up the main cancer cell population in epithelial cSCCs and their frequency decreased during cSCC progression." (PMID 39075581, 2024). "Further changes in phosphosite composition were observed between epithelial EpCAM+ plastic and mesenchymal EpCAMneg cancer cells, showing 302 upregulated proteins in EpCAM+ plastic vs. EpCAMneg cancer cells." (PMID 39075581, 2024). "Although several studies have shown EpCAM+ CTCs as prognostic biomarkers in different cancer types, very few studies have evaluated c-MET expression in CTCs." (PMID 38238761, 2024). "In this case, anti-CTLA-4 and anti-TIGIT therapies not only led to a reduction in the percentage of mesenchymal EpCAM− cancer cells but also induced the enrichment of epithelial EpCAM+ cancer cells." (PMID 38914547, 2024). "Tucotuzumab celmoleukin (huKS-IL2), an immunocytokine that acts by genetically fusing interleukin-2 (IL-2) to a humanized monoclonal antibody against EpCAM, has demonstrated safety and immunologic activity in cancer patients." (PMID 39595576, 2024). "The high level of EpCAM expression in many malignant tumors prompted the active development of drugs for EpCAM-directed targeted therapy." (PMID 39199590, 2024). "A variety of proteins can be targeted as biomarkers for isolation of sEVs including the tetraspanins CD9, CD63, CD81 and cancer-related markers such as EpCAM, CD24, and CA125." (PMID 38811455, 2024). "EpCAM+ cancer cells from MD/PD-SCCs showed variable levels of EpCAM expression and were classified as EpCAMhigh and EpCAMlow; by contrast, cancer cells from WD-SCCs exhibited a high level of EpCAM expression and were named full epithelial cancer cells." (PMID 38914547, 2024).
cancer (continued). "Immunohistochemical analysis of 106 KIRC patients’ samples revealed a substantial reduction in EpCAM protein levels within both paired and unpaired cancer tissues in comparison to normal tissues." (PMID 38187284, 2024). "To test the plastic behavior of epithelial ITGAV+ cancer cells, we engrafted EpCAM+ITGAV+ and EpCAM+ITGAV− cancer cells isolated from mixed cSCCs into immunocompetent syngeneic mice." (PMID 39075581, 2024). "Specifically, various devices have been developed that positively select for EpCAM, a transmembrane glycoprotein expressed in epithelial tissues, cancer stem cells, inflammatory diseases and, most importantly, epithelial cancers." (PMID 38607014, 2024). "A peptide, or protein fragment, has been developed to bind specifically to EpCAM, a molecular target expressed uniquely by cancer cells and to concentrate in tumors." (PMID 39199591, 2024). "Clusters were annotated based on expression of representative marker genes, as previously reported: those included EPCAM for epithelial cells, PTPRC for CD45-positive immune cells, VCAM1 for cancer-associated fibroblasts, and VWF for endothelial cells." (PMID 39122703, 2024). "EpCAM has a prominent expression in multiple types of cancer and is considered a target for monoclonal antibody-mediated (mAb) cancer therapy, first and foremost in colorectal cancer." (PMID 39199590, 2024). "In contrast, the engraftment of GFP+EpCAM+ cancer cells from MD/PD-SCCs gave rise to tumors with a variable percentage of GFP+EpCAM− cancer cells, and GFP+EpCAM− cancer cells from MD/PD-SCCs exclusively generated PD/S-SCCs." (PMID 38914547, 2024). "EVs are rich in membrane proteins and, when released from cancer cells, carry established tumor-associated antigens (TAAs) like Her2, CEA, EpCAM, etc.." (PMID 39329747, 2024). "To identify pathways potentially involved in EMP acquisition, we compared the proteins with phosphosites upregulated in EpCAM+ plastic vs. full epithelial cancer cells with those upregulated in EpCAM+ plastic cancer cells vs. EpCAMneg cancer cells." (PMID 39075581, 2024). "Our findings were in accordance with the database results, demonstrating a notable decline EpCAM expression within cancer tissues in our clinical specimens." (PMID 38187284, 2024). "Given that EpCAM and CD44v6 are markers of metastasis and cancer stemness, these observations support the role(s) of tumor NOS2 and COX2 expression as key targets of disease progression in breast and other tumors." (PMID 39356141, 2024). "Catumaxomab (anti-CD3 × anti-EpCAM), the first BsAb approved for cancer treatment, heralded the beginning of a new era in cancer therapy with the advent of BsAbs." (PMID 39068460, 2024). "The CTCs have variable expression for the epithelial and cancer-specific markers, such as EpCAM, EGFR, E-cadherin, mammaglobin, HER2, ER, and AR." (PMID 39594700, 2024). "This activation ultimately induces cancer stem cell properties in cell lines containing EpCAM-positive LCSCs." (PMID 39199400, 2024). "Epigenetic regulation is another common mechanism to control the expression of EpCAM in various cancer tissues and cells." (PMID 38791091, 2024). "LCAs derived from adenocarcinomas (ACs) of different patients maintained the intertumoral heterogeneity of cancer cell differentiation degree, and the expression patterns of EpCAM, cytokeratin 7 (CK7) and Ki67 were also retained in the LCAs." (PMID 38643164, 2024). "EpCAM serves not only as a regulator of normal epithelial cell functions but also as a focal point in cancer research, being identified as a marker for cancer stem cells (CSCs) in solid tumors." (PMID 39184916, 2024). "In this study, we present a dual-antibodies nanomagnetic bead-based separation method designed for cancer patients and EpCAM-independent CTCs detection." (PMID 38831912, 2024). "The CellSearch® system showed that EpCAM+ CTCs were correlated with poor prognosis in cancer patients." (PMID 38238761, 2024).